INS (insulin)
Diseases named in the same sentence as INS in open-access papers (continued):
Sharing a sentence is not in itself a finding about the gene and the disease.
Hyperinsulinemia (continued). "These phenotypes are similar to those reported in mice with IR or IRS deficiency, in which impaired insulin signaling in peripheral tissues promotes a ‘pre-diabetic’ condition with adaptive hyperinsulinemia compensating for systemic insulin resistance while maintaining normoglycemia." (PMID 25101872, 2014). "The oral glucose tolerance test (OGTT) demonstrated that in patients with hemochromatosis, iron overload may cause the liver to develop insulin uptake and utilization disorders, thereby inducing hyperinsulinemia." (PMID 24926364, 2014). "Considering pathophysiologically, visceral obesity may be linked to decreased glucose tolerance with hyperinsulinemia, leading to reduced insulin-mediated glucose uptake." (PMID 23829196, 2013). "On the other hand, hyperinsulinemia may cause the saturation of hepatic insulin extraction capacity, which in turn reduced MCRI in the DYS monkeys." (PMID 23886319, 2013). "In terms of ongoing debate on role of hyperinsulinemia in tumor genesis there is a growing concern that drugs translating into increased levels of circulating insulin may represent a risk factor." (PMID 23476808, 2013). "It is generally accepted that IR is the most common cause of hyperinsulinemia; however, recent studies have revealed that IR might also be a result of prolonged exposure of high concentrations of insulin." (PMID 24288442, 2013). "The decreased adiponectin receptors may be due to hyperinsulinemia since it has been reported that insulin deficiency increased, but insulin replenishment decreased the expression of adipoR1/2 in animals in vivo." (PMID 22873349, 2012). "In addition to the intricate interaction among CVRF, hyperinsulinemia caused by exogenous insulin replacement can add to the complexity of this scenario." (PMID 23270560, 2012). "The mechanisms for this association are unknown, but hyperinsulinemia appears to have a role in tumor initiation and progression in insulin-resistant patients." (PMID 23226522, 2012). "Moreover, current insulin therapy methods are themselves a potential cause of hyperinsulinemia in these patients." (PMID 23270560, 2012). "Importantly, unlike other reported T2D loci, the rs2943641C allele was associated with increased fasting- and glucose-stimulated hyperinsulinemia and impaired insulin sensitivity." (PMID 21917432, 2012). "Since hyperinsulinemia has been implicated as a significant cause of anovulation, many investigators hypothesized that a reduction of systemic insulin serum levels would result in an improvement of ovulatory function and overall fecundity in PCOS women." (PMID 21605417, 2011). "The ability of metformin to lower circulating insulin may be particularly important for the treatment of cancers known to be associated with hyperinsulinemia, such as those of the breast and colon." (PMID 21470407, 2011). "Using a rat model of semistarvation-refeeding in which catch-up fat is driven solely by elevated metabolic efficiency associated with hyperinsulinemia, we previously reported that insulin-stimulated glucose utilization is diminished in skeletal muscle but increased in white adipose tissue." (PMID 21244699, 2011). "IGFBP-1 and IGFBP-2 levels are inversely associated with insulin levels, which suggests that chronic hyperinsulinemia could depress binding protein interaction and thus increase free IGF-I." (PMID 20148110, 2010). "Several mechanism have been suggested to explain why central obesity is a risk factor of colon adenoma; visceral fat influences on insulin resistance via a portal effect of free fatty acids, resulting in hyperinsulinemia and increased free insulin-like growth factor (IGF-I)." (PMID 19144203, 2009). "Excessive production andinsufficient clearance of Aβ lead to its extracellular deposition as plaque.One way in which Aβ metabolism can fail is through hyperinsulinemia, caused bythe increase of insulin resistance through aging, because insulin stimulates Aβsecretion to the extracellular space." (PMID 19415148, 2008).
Hyperinsulinemia (continued). "This inverse association is biologically plausible in light of the previous literature detailing the insulin-lowering and glucose-sensitizing effects of physical activity as well as the potential relationship between hyperinsulinemia and pancreatic cancer risk." (PMID 18307811, 2008). "Therefore, we report the finding of UCP2 coding variants in human congenital hyperinsulinism, which reveals a role for this gene in the regulation of insulin secretion and glucose metabolism in humans." (PMID 19065272, 2008). "As a consequence, decreased fatty acid uptake by adipocytes and/or excessive lipolysis could cause high plasma NEFA concentrations, hyperinsulinemia and defective insulin-mediated glucose utilization in skeletal muscle." (PMID 17849011, 2007). "The changes in PL composition induced by the β3-AR agonist may be associated with the previously reported improved insulin sensitivity in adipose tissue, and the decrease of hyperinsulinemia measured in the present study." (PMID 15507149, 2004). "Conversely, some studies suggest that long-term use of exogenous insulin or insulin secretagogues may slightly increase pancreatic cancer risk, possibly because hyperinsulinemia persistently activates the insulin/IGF-1 receptor pathway and promotes cell proliferation." (PMID 41601937, 2026). "Up to 80% of the insulin released by the pancreas is extracted by the liver and the loss of the insulin receptor on the plasma membrane may decrease the amount of insulin extracted which then could drive hyperinsulinemia downstream in the peripheral tissues." (PMID 40040471, 2025). "As discussed by the authors, although hyperinsulinemia may be a risk factor for atheromatosis, a reasonable daily amount of insulin used for treatment and properly adjusted to diurnal glucose variability can attenuate the severity and progression of vascular damage." (PMID 39998445, 2025). "Obesity and T2D are also associated with hyperinsulinemia and increases in circulating cytokines, branched chain amino acids (BCAAs), and other metabolites, which can, directly and indirectly, affect liver metabolism by altering insulin signaling and substrate delivery to the liver." (PMID 40231468, 2025). "Thus, both increased pancreatic insulin secretion and decreased hepatic insulin extraction may cause hyperinsulinemia." (PMID 41009753, 2025). "Hyperinsulinemia may be further caused by decreased hepatic insulin clearance." (PMID 41009753, 2025). "IR refers to the decreased or impaired sensitivity of target organs or target tissues to insulin, which is manifested as impaired glucose uptake and utilization, and this pathological response causes insulin secretion disorders, which elevate plasma insulin levels and lead to hyperinsulinemia." (PMID 40881124, 2025). "Building upon this concept, and following the identification of hyperinsulinism as a specific metabolic hallmark in migraine patients, my research group developed and implemented a modified version of the Mediterranean diet tailored to individuals with insulin-related dysregulation." (PMID 40426647, 2025). "Based on biochemical evidence and current knowledge about the regulation of insulin secretion, a potential disease‐causing mechanism for underlying hyperinsulinism may involve a defect in intracellular lipoic acid availability that we demonstrated in our patient." (PMID 41030468, 2025). "Therefore, considering the pivotal role of insulin in the context of phthalates and gallstones, we hypothesize that phthalates may elevate the risk of gallstones by inducing hyperinsulinemia." (PMID 38903577, 2024). "In conclusion, hyperinsulinemia causes hyperuricemia and insulin could increase SUA levels." (PMID 38579756, 2024).
Hyperinsulinemia (continued). "Low SCFAs may also explain the fact that Black ≤ 2 times/wk HFCS sweetened beverage consumers had significantly higher hyperinsulinemia (7.3%) than White multiple times/d consumers (4.0%), because low SCFAs is associated with lower insulin clearance and higher odds of dysglycemia." (PMID 39075463, 2024). "Therefore, pancreatic β-cells increase the synthesis and release insulin, causing hyperinsulinemia." (PMID 38392069, 2024). "However, hyperinsulinemia may be caused by decreased liver regulation of insulin, hyper-glucagonemia is mainly because of elevated pancreatic discharge." (PMID 39040780, 2024). "High dose of insulin treatment (200 nM) significantly decreased mRNA expression levels of ERα in primary hepatocytes, suggesting that decreased hepatic ERα mRNA expression in diabetic patients may be caused by hyperinsulinemia." (PMID 38649684, 2024). "Furthermore, the idea that milk is beneficial is challenged by evidence that milk has strong insulin secretory activity, which may cause acute hyperinsulinemia and exacerbate IR." (PMID 39272602, 2024). "Elevated abdominal adiposity, displaying strong associations with elements including hyperinsulinemia, anomalies in insulin function, and modifications in systems of the IGF realm, might have influenced the probability of colorectal cancer development and the resulting fatality rates." (PMID 38904048, 2024). "Give the links between abnormal endometrium and conditions associated with hyperinsulinemia, we hypothesized that insulin may have a direct impact on endometrial epithelia, and that the response to insulin would be altered in cells that have acquired a PIK3CA mutation." (PMID 37170094, 2023). "However, there are concerns about the use of statins in premenopausal women as they are known to be teratogenic and have conflicting effects on glucose; some studies show a reduction in insulin levels after statin administration while others show an association with hyperinsulinemia." (PMID 37062827, 2023). "Furthermore, hyperinsulinemia might facilitate the development of central insulin and leptin resistance and be the underlying cause for the onset of hyperphagia in nutritional phase 2b and lack of satiety in phase 3." (PMID 37546289, 2023). "We have shown that in rats and mice with hyperinsulinemia and severe IR, the level of insulin in the hypothalamus and other brain regions is reduced, which indicates the development of insulin deficiency in the CNS under conditions of systemic hyperinsulinemia." (PMID 36834685, 2023). "Also, it has previously been reported that adherence to a lifestyle with a higher score of ELIH may be associated with an increased risk of insulin metabolism-related disorders, including IR, insulin insensitivity, and hyperinsulinemia." (PMID 35578225, 2022). "Notably, insulin values greater than 8.3 μU/mL are associated with suppression of lipolysis so that the observed reduction of insulin from 10.2 μU/mL to 8.3 μU/mL in the blueberry group is a clinically meaningful correction of hyperinsulinemia." (PMID 35458181, 2022). "extended this work and observed a ~2-fold decrease in plasma insulin 5-weeks following a switch from a HFHS diet to either a BCAA or AA deficient diet which was associated with reduced β-cell mitochondrial membrane potential (a marker of basal hyperinsulinemia)." (PMID 35355560, 2022). "If the association between FAORs and insulin or c-peptide levels in cord blood or amniotic fluid is defined through investigation, FAORs which we measured could be used as a surrogate marker for fetal hyperinsulinemia." (PMID 34893662, 2021). "However, the systemic hyperinsulinemia caused by reduced hepatic insulin clearance may also act as a stressor of peripheral tissues perturbating peripheral insulin sensitivity." (PMID 33498493, 2021).
Hyperinsulinemia (continued). "Since hyperinsulinemia has been identified as an early metabolic dysfunction indicator previously, several studies explored the association of these two indices with the risk of chronic diseases, in which impaired insulin balance plays an important role in their pathogenesis." (PMID 33985566, 2021). "Therefore, hyperinsulinemia is the first hallmark of reduced insulin sensitivity." (PMID 32737757, 2021). "On the other hand, hyperinsulinemia in overweight/obese subjects is associated with increased extremity muscle mass, which is partially reversible with reduction in fasting insulin concentration, consistent with the stimulatory effects of insulin on skeletal muscle after treadmill exercise." (PMID 34948944, 2021). "In addition, insulin has also been shown to influence glucose metabolism through the regulation of cyclin D1-cyclin dependent kinase (Cdk) 4 activity, rendering hyperinsulinemia-associated tumor growth susceptible to CDK4 inhibitors in the context of liver cancer." (PMID 33604295, 2020). "In addition, hyperinsulinemia, associated with insulin resistant conditions, may contribute per se to the urinary magnesium depletion, while reduced insulin sensitivity may itself affect magnesium transport." (PMID 33396570, 2020). "Regarding the potent neurotrophic effect of insulin, recent studies have indicated that beside glucose toxicity, insulinopenia and hyperinsulinemia may be important pathogenic components of diabetic peripheral neuropathy and visceral hypo- and hypersensitivity." (PMID 32260335, 2020). "A high-fructose diet can cause hyperinsulinemia, while a high-fat diet can result in impaired pancreatic function of insulin secretion and glucose intolerance, indicating that a high-fructose diet and a high-fat diet may exert divergent effects on glucose metabolism in rats." (PMID 31935815, 2020). "Furthermore, an in vitro study showed that insulin directly stimulates aromatase activity in both endometrial glands and stroma, which strongly suggests that hyperinsulinemia caused by IR predisposes to EC by enhancing endogenous endometrial estrogen production." (PMID 32911852, 2020). "Presumably, the association between hyperinsulinism and CH is underestimated as diagnostic options for CH by echocardiography have improved only in the last decades and since many case reports have incomplete clinical and laboratory information including missing insulin levels." (PMID 31840185, 2020). "CL has also been shown to stimulate insulin secretion, which may contribute to its ability to increase glucose uptake; however, CL has been shown to reduce obesity-associated hyperinsulinemia." (PMID 30804793, 2019). "Clearly, insulin therapy causes chronic peripheral hyperinsulinemia, and several studies have attempted to clarify whether long-term treatment with insulin or insulin analogs may increase the risk of overall cancer mortality and incidence in patients with T2DM." (PMID 29184536, 2017). "Furthermore, some of the variants like heterozygous E1506K pathogenic variant in the ABCC8 gene resulting in congenital hyperinsulinism in infancy, loss of insulin secretory capacity in early adulthood, and autosomal dominant diabetes in middle age in different members." (PMID 28095440, 2017). "Usually, diabetic patients have hyperinsulinemia and are associated with reduced insulin sensitivity and compensatory hyperinsulinemia as well as an increased insulin-like growth factor (IGF)-1 level, which may stimulate cell proliferation in pancreas, colon, breast, and other organs." (PMID 26541196, 2015). "Thus, elevated levels of glucose along with increase in insulin suggest that metabolic conditions such as hyperinsulinemia could be an added risk for the incidence of CVD." (PMID 25762868, 2015). "In addition, anandamide has been shown to stimulate insulin secretion in vitro, suggesting that anandamide might be linked to hyperinsulinemia." (PMID 25855974, 2015).
Hyperinsulinemia (continued). "Furthermore, orally delivered insulin reaches systemic circulation after passing through liver similar to physiological insulin secretion while injected insulin may result in peripheral hyperinsulinemia and associated complications." (PMID 26498972, 2015). "However, in the setting of eNOS deficiency, hyperinsulinemia may largely stimulate the latter endothelial insulin signaling." (PMID 25371905, 2014). "Given the association between hyperinsulinemia and pancreatic cancer, it has been suggested that excessive secretion of insulin by pancreatic β-cells required to maintain glucose homeostasis may directly influence pancreatic carcinogenesis in at-risk individuals." (PMID 25373319, 2014). "Diabetic individuals normally have hyperinsulinemia and are associated with reduced insulin sensitivity and compensatory hyperinsulinemia as well as increased insulin-like growth factor (IGF)-1 levels, which may stimulate cell proliferation in liver, pancreas, colon, ovary, breast, and other areas." (PMID 24884617, 2014). "In addition, eNOS deficiency and hyperinsulinemia may induce abnormal endothelial insulin signaling and cause vascular disorders." (PMID 25371905, 2014). "Besides, insulin could also indirectly affect UA, since there is an association between hyperinsulinemia and hypertriglyceridemia." (PMID 23311699, 2013). "Thus, insulin signaling may be decreased mainly under fasting conditions in the HF-diet group, as hyperinsulinemia associated with HF diet feeding may suppress Irs2 expression." (PMID 24284392, 2013). "Since hyperglycemia is associated with hyperinsulinemia, coinciding with the onset of laminin accumulation in the kidney in db/db mice, augmented laminin mRNA translation could be due to either elevated glucose or high insulin." (PMID 22454628, 2012). "Therefore, strategies that screen patients' insulin levels and therapies that specifically target hyperinsulinemia may have value to prevent this common risk factor for CVD." (PMID 22129309, 2011). "Accordingly, during chronically elevated circulating FFA levels it is hypothesized that the synergism of both glucose- and lipid-stimulated insulin-secretion elevates the basal insulin secretion causing hyperinsulinemia which may eventually exhaust the β-cell and desensitize the insulin receptors." (PMID 21211036, 2011). "On that same day, the patient also presented with hyperinsulinemia, a casual blood glucose level of 257 mg/dL, and an immunoreactive insulin level of 21.7 μU/mL." (PMID 41536580, 2026). "Hyperinsulinemia was classified as fasting insulin ≥ 15mIU/ml and/or stimulated insulin ≥ 80 mIU/ml and IR as HOMA-IR > 2.5." (PMID 41826956, 2026). "For instance, diets aligned with MQI principles—emphasizing whole grains, legumes, nuts, seafood, and plant-based fats—enhance insulin sensitivity and reduce postprandial glycemic variability, thereby mitigating hyperinsulinemia-driven cell proliferation." (PMID 41601909, 2026). "Although PAHSAs remain at an experimental stage, their insulin-sensitizing and anti-senescence effects provide compelling proof-of-concept that targeting hyperinsulinemia and its downstream consequences can modulate cellular senescence." (PMID 41189469, 2026). "The core mechanisms harnessed by antidiabetic agents—lowering hyperinsulinemia, enhancing insulin sensitivity, and mitigating cellular senescence—are also engaged by lifestyle interventions." (PMID 41189469, 2026). "Serum insulin levels were markedly elevated at 2778 μU/mL, while C-peptide levels were normal (5.04 ng/mL), and anti-insulin antibodies were high (43 U/mL), confirming endogenous hyperinsulinemia due to IAS." (PMID 41589093, 2026). "By improving glucose uptake and reducing insulin demand, exercise mitigates hyperinsulinemia, thereby preventing insulin-induced cellular senescence." (PMID 41189469, 2026).